RNU6-1264P (RNA, U6 small nuclear 1264, pseudogene)
Gene: Small nuclear RNA gene on chromosome 17 (6,207,163 to 6,207,269, forward strand). Ensembl gene ENSG00000206618.
Homologues: Orthologues: chimpanzee U6 (99% identical), macaque U6 (93% identical). Paralogues in human: RNU6-116P (86% identical), RNU6-1060P (85% identical), RNU6-15P (85% identical), RNU6-33P (85% identical), RNU6-959P (85% identical), RNU6-1 (84% identical), RNU6-1019P (84% identical), RNU6-14P (84% identical), RNU6-2 (84% identical), RNU6-3P (84% identical), RNU6-455P (84% identical), RNU6-468P (84% identical), and 1284 more.